CXCR2 (C-X-C motif chemokine receptor 2)
Diseases named in the same sentence as CXCR2 in open-access papers (continued):
Sharing a sentence is not in itself a finding about the gene and the disease.
tumor (continued). "Along this view, Leslie and colleagues have recently reported that antagonizing CXCR2 in neutrophils sensitizes mice harbouring NASH-HCC to anti-PD-1 immunotherapy reducing the tumor burden and increasing the survival rate." (PMID 36691794, 2023). "The role of chemokine receptor-2 (CXCR-2) and other cell signal transduction and protein expression related to tumor metastasis directly promotes the metastasis of ovarian cancer tumor cells." (PMID 38030996, 2023). "CXC chemokine and its homologous receptor CXC chemokine receptor 2 (CXCR2) play a key role in tumor growth and angiogenesis." (PMID 37576896, 2023). "Another cell type known to acquire a pro-tumorigenic phenotype within the TME is the neutrophil; MIF, through the binding of CXCR2, promotes their tumor infiltration." (PMID 36672343, 2023). "In the literature, blocking of the CXCL2-receptor (CXCR2) mediated a reduced tumor outgrowth, and decreased tumor volumes, at least preclinically in orthotopic GBM mouse models." (PMID 38069130, 2023). "We previously demonstrated that targeted deletion of Cxcr2 in myeloid cells or systemic treatment with the CXCR1/CXCR2 antagonist SX-682 conferred anti-tumor immunity via reduction of MDSC infiltration into the TME and enhanced CD8 + T cell activation." (PMID 37270599, 2023). "Tumor tissue samples were examined for any relationship between CXCL6/CXCR2 activity and patient prognosis." (PMID 37509721, 2023). "Both CXCL1 and CXCL2 are ligands of CXCR2, which promotes tumor growth and progression by inhibiting the cytotoxic activity of CD8+ T cells." (PMID 36713833, 2023). "Mechanistically, intratumoral P. gingivalis recruited tumor-associated neutrophils by increasing the secretion of neutrophilic chemokines (C-X-C motif chemokine ligand 1 (CXCL1), CXCL2, C-X-C motif chemokine receptor 2 (CXCR2), IL-17F, S100a8 and S100a9)." (PMID 37868956, 2023). "Overall, there are many reports showing that upregulation of CXCR2 signaling in different cancers contributes to tumor immunity and development, angiogenesis, metastasis and drug resistance." (PMID 36903345, 2023). "We clearly observed that loss of CXCR2 expression in tyrosinase-expressing cells where there was expression of mutant BRAF and loss of PTEN resulted in reduced tumor growth and lowered incidence of tumor formation." (PMID 37270599, 2023). "Strikingly, almost all neutrophils expressed CXCR2 in tumor-bearing mice, whereas only small percentages of monocytes (3%), macrophages (19%), and dendritic cells (22%) expressed CXCR2." (PMID 38067390, 2023). "For example, human HCC tumor tissues and cell lines express high levels of CXCR2 ligands, whereas T cells lack CXCR2." (PMID 37596653, 2023). "Our finding that neutrophils highly and preferentially express CXCR2 in both periphery and TME in tumor-bearing mice provides a mechanistic insight on the exclusive blocking effect of the CXCR2 antagonist on neutrophils." (PMID 38067390, 2023). "Tumor-derived IL-8, the most abundantly expressed C-X-C motif chemokine receptor 2 (CXCR2) ligand, can induce NETosis in a variety of cancers by interacting with the CXCR2 receptor on neutrophils." (PMID 36942262, 2023). "Approximately 70% of the tyrosinase expressing GFP-positive tumor cells expressed CXCR2 in the tumors arising in Braf/Pten/CXCR2WT model and 30% of the tyrosinase expressing GFP + tumor cells in the Braf/Pten/Cxcr2−/− model continued to express CXCR2." (PMID 37270599, 2023). "In tumor-bearing mice, treatment of CXCR2 antagonist reduces MDSCs migration to the peritoneal cavity." (PMID 37932814, 2023). "Increased expression of CXCR2 triggers the release of bone marrow neutrophils into the circulation and promotes their subsequent recruitment to the tumor microenvironment." (PMID 36921037, 2023). "CXCR2 blockade showed the same effects on RT-induced tumor inhibition and host survival as direct neutrophil depletion." (PMID 38067390, 2023).
tumor (continued). "CXCL1 is a chemotactic factor that recruits MDSCs into the tumor microenvironment by binding to its receptor CXCR2." (PMID 37865804, 2023). "CXCL1 and CXCR2 are known to have a regulatory role in tumor cell migration, invasion, and metastasis in a variety of cancers." (PMID 36614235, 2023). "Another study also showed that CXCR2 inhibition significantly reduced NET-primed tumor growth in lymphoma-bearing mice." (PMID 36050539, 2023). "Since there are reports that CXCL5 binds to C-X-C motif chemokine receptor 2 (CXCR2) to promote angiogenesis, tumor growth, and metastasis, we examined the role of CXCR2 in VSMC migration." (PMID 37373052, 2023). "Previous studies have revealed that CXCL1 and its receptor CXCR2 are involved in the angiogenesis, tumorigenesis and metastasis of different types of tumours, such as rectal cancer, breast cancer and HCC." (PMID 37037815, 2023). "Consistent with previous findings, flow cytometric analysis indicated that neutrophils from the bone marrow and blood of OT mice expressed high levels of CXCR2 comparable to those of sham, non-tumor bearing controls." (PMID 36614196, 2023). "We also examined CXCR2 expression on tumour cells, although this was rare in this cohort selected for adenocarcinoma tumour histology." (PMID 37844613, 2023). "To confirm the anti-tumor effects of RT-induced neutrophils and to compare the CXCR2 blockade effects with neutrophilic depletion, in a separate experiment, we depleted neutrophils by injecting anti-Ly6G antibody one day before tumor radiation." (PMID 38067390, 2023). "CXCL5 is a chemokine that promotes tumor formation by triggering the migration of CXCR2+ immune cells to tumors." (PMID 36980564, 2023). "In agreement with the mMCPcounter predicted leukocytic infiltrates, we observed that deletion of Cxcr2 in melanocytes undergoing transformation skewed the TME toward anti-tumor immunity." (PMID 37270599, 2023). "Studies previously done by researchers suggested that blockade of the CXCR2 axis decreased tumor angiogenesis and PDAC invasion." (PMID 37784082, 2023). "The treatment of Reparixin, the pharmacological inhibitor of CXCR1 and CXCR2, caused the significant reduction of G-MDSCs numbers, in colon adenocarcinoma HT29 xenograft tumor and colon carcinoma CT26-GM-derived subcutaneous tumor models." (PMID 37006306, 2023). "IFN-γ activates the RhoGDI2/Rac1/NF-κB pathway in tumor cells to reduce the production of the pro-tumor cytokine CXCL8, promoting tumor apoptosis and reducing CXCR2+ M2 macrophages." (PMID 37275859, 2023). "To determine if chemokine receptor CXCR2 is involved in RT-induced neutrophilic infiltration into the tumor, we blocked the ability of CXCR2 to bind to its corresponding ligands by treating mice with CXCR2 antagonist AZD5069." (PMID 38067390, 2023). "We observed that neutrophil recruitment to the tumor was impaired compared to CXCR2+/+ WT OT controls." (PMID 36614196, 2023). "On the contrary, oxidative neutrophils (ckit+CXCR2- phenotype) in the tumor microenvironment suppress anti-tumor immunity through IFN-γ." (PMID 38259490, 2023). "Arnt−/− mice had more CD11b+Gr1+ neutrophil infiltration, fewer proinflammatory factor TNFα production, more anti-inflammatory factor IL-10 production and CXCR2 expression in neutrophils in tumor and draining lymph node (dLN) compared with WT control." (PMID 36859266, 2023). "CRC cells are able to regulate CXCL8 in an autocrine manner and increase the expression of CXCR1 and CXCR2, which contributes to tumor development through the invasion, dissemination and metastasis of cancer cells." (PMID 37509572, 2023). "Data from both in vivo and in vitro models showed that the CXCR2/CXCL1 axis as well as the CXCR2/CXCL5 axis regulate neutrophil infiltration into tumor tissues, inducing epithelial–mesenchymal transition and thus aggravating malignant behavior of HCC cells." (PMID 36982370, 2023).
tumor (continued). "This is further enhanced by infiltration of CXCR1- or CXCR2-expressing MDSCs, which further promote tumor growth by inhibiting local anti-tumor immune responses mediated by CD8+ T-lymphocyte infiltration and cytotoxicity." (PMID 36725964, 2023). "The CXCL5/CXCR2 axis favors migration and invasion in BC cell lines, increasing MMP-2/-9 levels through the PI3K/AKT pathway, and CXCL5 has been linked to tumor grade, muscle invasion, and poor OS." (PMID 36614308, 2023). "CXCL1, CXCL2, CXCL5, and CXCL8 can mediate MDSC recruitment and accumulation at the tumor site via CXCL–CXCR1/CXCR2 interactions." (PMID 37547175, 2023). "Positive predictive values (PPV) for CXCL8 and CXCR2 were higher than for the classical tumor marker CA19-9." (PMID 37240178, 2023). "These varying aspects between CXCR1 and CXCR2 lead to more questions about how they function in the tumor microenvironment, specifically pertaining to how they affect tumor cells." (PMID 36831112, 2023). "CXCR2-positive MDSCs are recruited into the tumor microenvironment via chemokines CXCL1 and CXCL2 mainly expressed in tumor colonic epithelial cells, which is critical for colitis-associated tumor formation and progression." (PMID 37124519, 2023). "Since CXCR2 blockade significantly decreases RT-induced neutrophils in the tumor, we next sought to determine if this reduction of neutrophilic infiltration translates into diminished anti-tumor effects of radiation." (PMID 38067390, 2023). "Although tumor growth increased CXCR2 expression on lymphoid cells, the percentages of CXCR2+ cells were below 1% in these populations, indicating that CXCR2 blockade would not have significant effects on lymphoid populations." (PMID 38067390, 2023). "CXC (such as CXCL1, CXCL2, CXCL5, CXCL6, and CXCL8) at the tumor site involve CXCR2+ neutrophils that differentiate into TANs." (PMID 36980182, 2023). "Compared to other immune cells, neutrophils highly and preferentially express CXCR2, which explains the exclusive blocking effects of the CXCR2 antagonist on neutrophil recruitment into the tumor." (PMID 38067390, 2023). "IFN-γ can also block the interleukin 8-chemokine receptor CXCR2 (CXCL8-CXCR2) axis, which prevents the timely transportation of CXCR2+ CD68+ immunosuppressive macrophages to the tumor microenvironment (TME)." (PMID 37927510, 2023). "The following year, the same team reported that METTL3 inhibited anti-tumor immunity by targeting the m6A-BHLHE41-CXCL1/CXCR2 axis to promote CRC cell proliferation." (PMID 37580808, 2023). "We observed significantly reduced tumor volume with deletion of Cxcr2 (360 ± 285mm3) when compared to NRas/Ink4a/Cxcr2WT mice (764 ± 601mm3) (p < 0.05, n = 16)." (PMID 37270599, 2023). "CXCR2 is also significant in metastasis—if circulating tumor cells express CXCR2, then such cells will metastasize in organs with the high expression of ligands for this receptor." (PMID 35216283, 2022). "It has been observed that neutrophils simultaneously expressing both CXCR2 and CXCR4 in the TME are associated with a N2-like tumor-promoting state." (PMID 36347862, 2022). "Recent studies indicated that the CXCLs/CXCR2 axis contributes to tumor progression in HCC through the infiltration of neutrophils and myeloid-derived suppressor cells." (PMID 36403057, 2022). "CXCR2 inhibition also suppressed the increase in tumor cell transendothelial migration in response to CXCL1." (PMID 36077870, 2022). "More importantly, compared to the classical tumor marker CEA, the serum CXCL8 and its receptor CXCR2 are more valuable on the diagnostic sensitivity, predictive value of negative results, and accuracy." (PMID 35935996, 2022). "Neutrophils have high expression of CXCR1 and CXCR2, both of which interact with their ligands secreted by tumor cells, stromal cells, endothelial and immune cells in the TME, thus promoting their recruitment to tumor sites." (PMID 36514901, 2022).
tumor (continued). "For example, primary CRC tumor-secreted VEGF-A stimulated tumor-associated macrophages to produce CXCL1, which recruited CXCR2-positive myeloid-derived suppressor cells (MDSCs) accumulated in the pre-metastatic site and facilitated liver metastasis." (PMID 36348319, 2022). "CXCL2 binds to CXCR2, which in turn couples with Gαi to stimulate neutrophil chemotaxis and endothelial cell migration for tumor transformation and growth in CRC cells." (PMID 35954156, 2022). "In tumor tissue of resistant models increased levels of IL-17R, CXCR2 chemokines, and CXCR2 were observed in comparison to C166 tumor tissue." (PMID 35954312, 2022). "It has been reported that the CXCR1/CXCR2 axis regulates myeloid-derived suppressor cells (MDSCs) in the tumor environment." (PMID 35805071, 2022). "The number of CXCR2+ immune cells (mainly neutrophils) at the invasive edge of the primary tumour significantly correlated with CXCR2+ infiltrates at the margin of the matched liver metastases (rho = 0.612, p = 0.003)." (PMID 35879507, 2022). "In recent years, the CXCL5/CXCR2 axis has received increasing attention for its potential in cancer screening, tumor prognosis and personalized anticancer therapy." (PMID 35702353, 2022). "It has been reported that IL8 promoted angiogenesis by recruiting CXCR2+ neutrophils, which provided the growing neoplasm with pro-angiogenic mediators (VEGFs and MMPs), implicating IL8 as a druggable immunotherapeutic target." (PMID 35487914, 2022). "Chemokines CXCL1, CXCL2, and CXCL8 are highly expressed in Cancer Cells and act on CXCR1 and CXCR2, which are highly expressed in Neutrophil chemotactic the activity of Neutrophils and promote the generation of tumor immune microenvironment." (PMID 36401283, 2022). "Our results show that treatment with CCR2 and CXCR2 antagonists improves the effect of TACE to provide increased anti-tumor activity." (PMID 36403057, 2022). "During the tumor process, when the C-X-C motif chemokine receptor 2(CXCR2) is activated, the expression level of miR-449c targeting STAT6 mRNA in MDSCs is upgraded to promote the MDSC expansion." (PMID 35359390, 2022). "Another strategy is to inhibit neutrophil recruitment to the tumor microenvironment (CXCR2 antagonists)." (PMID 36555469, 2022). "When CXCL8 activates CXCR2, neutrophils infiltrate into tumor tissue and synthesize angiogenic factors, such as VEGF, to stimulate vascularization." (PMID 36612163, 2022). "In summary, our findings uncover a critical role for BRAF/TBX3/CXCLs signaling in the regulation of anti-tumor immunity and suggest the use of combination CXCR2 inhibitor with MAPKi therapy in patients with advanced PTC." (PMID 35332119, 2022). "The administration of INF-γ inhibited the tumor trafficking of CXCR2+ cells, suppressing the release of tumor-derived CXCL8, ultimately enhancing anti-PD1 efficacy." (PMID 35664746, 2022). "Studies on the mechanism of action of Gals-3 revealed that down-regulation of Gals-3 inhibits the expression of CXCL7 and CXCR2, thus suppressing tumor formation and colony formation capacity of renal cancer cells." (PMID 35837284, 2022). "CXCL5, a ligand for CXCR2, involved in immune cell recruitment and promotes angiogenesis, tumor development, and metastasis." (PMID 36186898, 2022). "The CSF-1R inhibitor and CXCR2 antagonist combination blocked tumor granulocyte infiltration and presented strong anti-tumor efficacy." (PMID 35585567, 2022). "We focused on the importance of CXCR2 in tumor processes such as proliferation, migration, and invasion of tumor cells as well as the effects of CXCR2 activation on angiogenesis, lymphangiogenesis, and cellular senescence." (PMID 35216283, 2022). "The inhibition of CXCR2 alone resulted in enhanced T cell infiltration, and when combined with checkpoint blockade or CSF-1R inhibition, tumor responses were enhanced." (PMID 35205732, 2022).
tumor (continued). "The recruitment of immune cells involved C-X-C motif chemokine ligand 5 (CXCR2), which promotes angiogenesis and tumor growth." (PMID 35924159, 2022). "Dual targeting of the CCR2+ TAMs and CXCR2+ TANs improved the anti-tumor immunity in pancreatic adenocarcinoma." (PMID 35585567, 2022). "Cytokines CXCL1, CXCL2, and CXCL8 in Cancer Cells interact with CXCR1 and CXCR2 in Neutrophils, chemotactic the activity of Neutrophils, and promote the generation of tumor immune microenvironment." (PMID 36401283, 2022). "Comparing neutrophils within CRC tissues to those infiltrating the tumour-adjacent mucosa, we observed an upregulation of the IL-8-responsive chemokine receptor CXCR2 on TANs." (PMID 35121727, 2022). "For example, CXCR2 blockade, which inhibits neutrophil recruitment to the tumor microenvironment, enhanced the efficacy of ICIs in several tumor murine models." (PMID 36555469, 2022). "The CXCLs/CXCR2 autocrine loop is also concerned with lung tumorigenesis and mediates tumor cell proliferation and epithelial–mesenchymal transition (EMT) by regulating the p38/ERK MAPK pathway." (PMID 36612163, 2022). "CAFs can additionally increase the expression of PD-L1 on tumor cell surfaces by expressing CXCL5, which engages CXCR2 on tumor cells and upregulates PD-L1 by activating PI3K/AKT signaling." (PMID 35345849, 2022). "This is in support of a previous study showing that in Lewis lung cancer orthotopic and heterotopic tumor model systems, rendering CXCR2 ineffective via gene knock-out or with a specific neutralizing antibody lowered tumor development and spreading potential." (PMID 36164329, 2022). "In xenograft tumor models, the combination of CXCR2 and PD-1 inhibitors significantly prolonged the survival of mice." (PMID 36324574, 2022). "Our data shows that small molecule CXCR2 antagonist AZD5069 not only effected a significant decrease in the influx of TANs toward the BrM tumor, but also a reduction in the overall density of the NETs produced by the infiltrating neutrophils." (PMID 35158784, 2022). "The combined CCR2 plus CXCR2 blockade enhanced the chemotherapeutic efficacy and improved the survival of tumor-bearing mice." (PMID 35664746, 2022). "Another study reported that overexpression of CXCL1 stimulates CXCR2+ endothelial cell migration and increases the formation of tumor microvessels in CRC patients." (PMID 35954156, 2022). "CXCL1 can directly recruit circulatory CXCR2-expressing neutrophils and MDSCs from the circulation into inflammatory sites and tumor tissues, promoting liver metastasis." (PMID 35954156, 2022). "The occurrence of a solid tumor and the consequently required mobilization of neutrophils to the tumor site depends on an axis of interactions among CXCR2 and its ligands CXCL1-3 and CXCL5-8." (PMID 35328639, 2022). "In cohort 2, there was a trend towards increased infiltration of CXCR2+ cells in patients with high stromal invasion in primary tumours (p = 0.088) and a significant increase in matched liver metastases (p = 0.037)." (PMID 35879507, 2022). "We first analyzed the impacts of pharmacological inhibition of NF-κB signaling in tumor cells or CXCR2 in PMN-MDSCs using a transwell migration assay." (PMID 36435834, 2022). "We also discuss the importance of CXCR2 in cell recruitment to the tumor niche including tumor-associated neutrophils (TAN), tumor-associated macrophages (TAM), myeloid-derived suppressor cells (MDSC), and regulatory T (Treg) cells." (PMID 35216283, 2022). "It promotes tumor progression by stimulation of C-X-C motif chemokine receptor 2 (CXCR2) ligand expression, which results in the induction of tumor-associated angiogenesis." (PMID 36081407, 2022). "FAPα promoted CXCL5 secretion in HSCs, which activated CXCR2 to promote the epithelial-mesenchymal transition of tumor cells and the recruitment of myeloid-derived suppressor cells." (PMID 35951441, 2022).